HRAS (HRas proto-oncogene, GTPase)
Diseases named in the same sentence as HRAS in open-access papers (continued):
Sharing a sentence is not in itself a finding about the gene and the disease.
Costello syndrome (74 papers, 2007 to 2026). "Coarse facial features and curly hair were evocative of Costello syndrome, and genetic testing revealed a heterozygous pathogenic mutation in the HRAS gene (c.34G>A), confirming the diagnosis." (PMID 40034618, 2025). "Although HRAS mutations are less common, the HRAS-G12S mutation is the predominant one in the very rare Costello syndrome." (PMID 41248180, 2025). "Earlier data examined the impact of Costello syndrome-associated HRAS-G12V and HRAS-G12S on cortical neuron development in vitro and after electroporation in utero." (PMID 41248180, 2025). "Other reported associations, such as hypertrophic cardiomyopathy with RAF1 mutations and ectodermal anomalies with HRAS mutations (Costello syndrome), were also partially recapitulated in our cohort, further validating established phenotypic correlations." (PMID 41292581, 2025). "Costello syndrome (CS) is a RASopathy caused by heterozygous gain-of-function germline mutations in HRAS, typically in the G12 position of HRAS (p.G12S variant)." (PMID 38672195, 2024). "The first case was one with a NT thickness of 11.7 mm, detected with a heterogenous missense mutation of NM_005343.4: c.38G > A (p.Gly13Asp) in HRAS gene, which was reported to lead to Costello syndrome." (PMID 37660152, 2023). "HRAS alterations were detected in only 2 out of 19 patients referred with a Costello syndrome suspicion, whereas pathogenic variants in RAF1 and SHOC2 were detected in 3 and 2, respectively." (PMID 37568403, 2023). "Another interacting protein, HRAS-germline mutations were involved in Costello syndrome, a multiple congenital anomaly and intellectual disability syndrome." (PMID 38025430, 2023). "Costello syndrome (CS) is a type of RASopathy caused mainly by de-novo heterozygous pathogenic variants in the HRAS gene located on chromosome 11p15.5." (PMID 35740842, 2022). "These disorders are generally termed as RASopathies and among them Costello syndrome (CS) is a distinctive entity that is caused by specific HRAS germline mutations." (PMID 36330334, 2022). "Costello syndrome (CS) is a congenital disorder caused by heterozygous activating germline HRAS mutations in the canonical Ras/mitogen-activated protein kinase (Ras/MAPK) pathway." (PMID 34553752, 2022). "Costello syndrome (CS) is a type of RASopathy caused mainly by de-novo heterozygous pathogenic variants in the HRAS gene, which is located on chromosome 11p15.5." (PMID 35740842, 2022). "WES detected a de novo pathogenic variant in the HRAS gene confirming Costello syndrome (OMIM 218040)." (PMID 36360323, 2022). "Costello syndrome (CS) has been described as a multiple congenital anomaly syndrome caused by heterozygous activating germline mutations in HRAS." (PMID 35230976, 2022). "To illustrate, Costello syndrome is caused by GOF mutations in the Harvey rat sarcoma viral oncogene homolog (HRAS) gene, whereas neurofibromatosis Type 1 is due to LOF mutations in NF1 gene." (PMID 35069188, 2021). "Costello syndrome is caused by mutations of HRAS, a proto-oncogene, and is one of the underlying diseases of quasi-MMD14." (PMID 33452387, 2021). "So is an HRAS-mutation definitively associated with Costello syndrome, and is a BRAF-mutation moderately associated with NS and definitively associated with cardiofaciocutaneous syndrome." (PMID 32394265, 2020). "Some of the identified genes are only associated with one disorder, examples are HRAS for Costello syndrome; and SHOC2 (OMIM 602775), RRAS (OMIM 165090), and CBL (OMIM 165360) for Noonan‐like syndrome." (PMID 30784236, 2019). "For Costello syndrome, mutations in HRAS (OMIM 190020) have been identified in 83%–100% of patients and is the only gene definitely associated with the syndrome thus far." (PMID 30784236, 2019).
Costello syndrome (continued). "Here we report that a mouse model for Costello syndrome (CS), which carries an activating mutation in the HRAS gene, shows hyperactivation of the RAS-ERK pathway, learning deficits, structural brain abnormalities, and alterations in synaptic functioning." (PMID 28455524, 2017). "Mutations in the HRAS gene that are associated with sporadic tumors are somatic; otherwise they result in the Costello syndrome phenotype." (PMID 28187001, 2017). "We report a patient with Costello syndrome (CS), who despite having the classical, severe, oncogenic p.Gly12Val mutation in HRAS has a mild clinical phenotype." (PMID 27195699, 2016). "Mutation of HRAS Gly60, a residue that normally contacts Arg68 and promotes a mild form of Costello syndrome, was recently reported to promote efficient binding to Raf but not to activate it." (PMID 28002430, 2016). "The diagnosis was confirmed by molecular tests, which identified c.35G > C (p.G12A) substitution in the HRAS gene, the second most common mutation responsible for Costello syndrome." (PMID 26812928, 2016). "Somatic mutations in HRAS are important drivers in cancer, and germline mutations cause Costello syndrome." (PMID 27195699, 2016). "Germline mutations in HRAS gene have been previously reported in individuals affected by Costello syndrome." (PMID 28002430, 2016). "Costello syndrome is an autosomal dominant inherited disorder with frequent de novo mutation in the HRAS gene." (PMID 25815234, 2015). "The germline p.G12S HRAS mutation has been causally linked to Costello syndrome, a complex developmental disorder characterizing by facial dysmorphism." (PMID 25980437, 2015). "Diagnosis with Costello syndrome was proved since the age of 3 by genetic testing which revealed a mutation (G12S) in the HRAS gene." (PMID 25815234, 2015). "This corroborates the finding that patient’s with Costello Syndrome (HRAS germline mutation), Noonan Syndrome (NRAS, KRAS, PTPN11 germline mutations) and Neurofibromatosis (NF1 germline mutation) all have increased risk of developing fusion-negative RMS." (PMID 25768946, 2015). "The deleterious mutation p.Glu63Lys has been identified in the GTPase HRas protein (UniProt: P01112) of patients with Costello syndrome (MIM: 218040)." (PMID 26173036, 2015). "Costello syndrome is caused by mutations in HRAS, NF1 by mutations in Neurofibromin and CFC syndrome by mutations in BRAF, KRAS and MEK1/2." (PMID 17222357, 2007). "Others are caused by point mutations in PTPN11 (Noonan syndrome) and HRAS (Costello syndrome)." (PMID 39459551, 2024). "Missense variants in the proto-oncogene HRAS underlie the RASopathy Costello syndrome (CS)." (PMID 35764878, 2022). "Costello syndrome (CS) is caused by heterozygous HRAS germline mutations." (PMID 35764878, 2022). "Costello syndrome is an autosomal dominant disorder that is caused by germline HRAS mutations." (PMID 32792500, 2020). "Although mutations at FGFR2 c.755 are a representative model for selfish mutations in general, further studies will be required to confirm the findings in other genes such as FGFR3 (associated with achondroplasia and thanatophoric dysplasia) and HRAS (associated with Costello syndrome)." (PMID 31348830, 2019). "Costello Syndrome patients with HRAS mutations exhibit increased TMS-induced plasticity." (PMID 31017896, 2019). "Costello syndrome (CS) is a rare RASopathy caused by activating mutations in the HRAS gene." (PMID 28455524, 2017). "Germline mutations in the HRAS gene result in Costello syndrome, which is characterized by growth imbalance during prenatal and postnatal development, an increased probability of oncogenesis, mental retardation, and skin, musculoskeletal, and cardiovascular abnormalities." (PMID 28187001, 2017). "Costello syndrome (CS) may be caused by activating mutations in codon 12/13 of the HRAS proto-oncogene." (PMID 27195699, 2016).
Costello syndrome (continued). "Germline mutations in HRAS cause Costello syndrome (CS) (MIM: 218040), which is a congenital disease characterized by postnatal growth retardation, short stature, tumor predisposition, developmental delay, and abnormalities of the heart (cardiomyopathy), skin and skeletal muscles." (PMID 27195699, 2016). "Costello syndrome associated with novel germline HRAS mutations: An attenuated phenotype?" (PMID 23024823, 2012). "Likewise, individuals with Costello syndrome, a condition that results from germline activating mutations in HRAS leading to the over-activation of the MAPK/ERK pathway, show defective enamel mineralisation with increased number, proliferation and irregular orientation of ameloblasts." (PMID 29541918, 2018). "However, it is possible that acanthosis nigricans which presented in our patient may serve as a direct correlation with HRAS mutation associated with Costello syndrome." (PMID 25815234, 2015). "Among this group of disorders, craniosynostosis appears to be consistently associated with Noonan, CFC, and Costello syndromes with pathogenic variants most frequently reported in BRAF, HRAS, KRAS, and PTPN11." (PMID 37774117, 2024). "Suppression of oncogenic HRAS signaling in Costello syndrome fibroblasts increases CHST11 expression." (PMID 37076815, 2023). "As is known, Noonan syndrome and phenotypically overlapping syndromes such as Costello syndrome and Leopard syndrome are part of the so-called rasopathies and are caused by at least 16 genes, PTPN11 and HRAS are the most prevalent genes." (PMID 37660152, 2023). "For instance, HRAS mutations, mutated in 6.6% HNSCC (but uncommon in other solid tumors), are also germline altered in Costello syndrome." (PMID 35296678, 2022). "Increased HRAS signaling causes down-regulation of C4ST-1 expression, and results in cell proliferation and defects in elastic fiber formation in Costello syndrome." (PMID 33452387, 2021). "Among the top ten protein hit, GTPase HRas which has been crucial role in formation of tumor, Costello syndrome and other type of cancers was found one with better fitness score." (PMID 30345469, 2018). "A de novo variant in HRAS at Lys117, the homologous equivalent of Lys128 in RALA, was found in two unrelated probands with Costello Syndrome." (PMID 30500825, 2018). "Lastly, a de novo HRAS variant at Ala146, the homologous equivalent of Ala158 in RALA, was reported in at least three patients with Costello Syndrome." (PMID 30500825, 2018). "Costello syndrome (CS, OMIM #218040) is caused by heterozygous germline mutations in the proto-oncogene HRAS that cause dysfunction of the Ras-MAPK signaling pathway." (PMID 26812928, 2016). "CFC and Costello syndromes are thought to be caused by gain-of-function mutations that activate the Ras/ERK pathway, whereas the MAP2K2 and HRAS variants that we identified in autism cases are most compatible with loss of protein function." (PMID 22558107, 2012). "Mutations in MAP2K2 and HRAS are responsible for cardiofaciocutaneous (CFC) and Costello syndrome, respectively, related monogenic disorders characterized by mental retardation, facial dysmorphism, cardiac defects and a high prevalence of autistic features." (PMID 22558107, 2012). "Costello syndrome is encoded by HRAS (11p15.5) and KRAS (12p12.1), and gain-of-function mutations influencing p.Gly13 or p.Gly12 may cause germline activation of HRAS, and thereby lead to dysregulation of the Ras-Raf-MEK-ERK signaling pathway." (PMID 34539540, 2021). "However consistent with previously reported mutations that contribute to Costello syndrome and other RASopathies, the Arg68Trp mutant activated the downstream Raf-MEK-ERK-Elk1 signaling pathway to a level intermediate between wild-type and oncogenic HRAS-Gln61Leu." (PMID 28002430, 2016). "Given the frequency of neonatal hypoglycemia in Costello syndrome, it seems that intrinsic mechanisms driven by mutant HRAS itself are involved, which are not known in detail." (PMID 37065762, 2023).
thyroid cancer (62 papers, 2013 to 2026). "After BRAF, activating mutations of RAS (NRAS >> HRAS > KRAS) are the next most common oncogenic drivers found in advanced thyroid cancers." (PMID 39874138, 2025). "HRAS, a distinct subtype within the Ras GTPase family implicated in thyroid cancer, had demonstrated that its expression in subcutaneous fat diminishes when caloric intake is restricted, thereby mitigating cancer signaling pathways in murine models." (PMID 41019282, 2025). "Several studies have confirmed the involvement of HRAS mutations in various cancers, including bladder, colon, head and neck, lung, and thyroid cancers." (PMID 37153521, 2023). "For instance, activating HRAS mutations have been found in up to 10% of thyroid cancers, linked with aggressive disease and poor prognosis." (PMID 37153521, 2023). "RAS mutations (including its variants, including NRAS, KRAS, and HRAS) are the most commonly mutated genes in thyroid cancer." (PMID 36613811, 2022). "In head and neck cancer, HRAS mutations are biased toward G12 and G13, whereas in thyroid cancer, HRAS mutations are most commonly observed at Q61." (PMID 28815022, 2017). "RAS mutations (KRAS, NRAS, and HRAS) are found at a relative low frequency in differentiated thyroid cancers compared with the more common BRAF mutations." (PMID 27127178, 2016). "HRAS is among the most documented genes whose mutations have been associated with thyroid cancer." (PMID 31349573, 2019). "Our WES analysis of the DNA extracted from the malignant thyroid tissue of patient III8 identified somatic heterozygote missense candidate variations in two genes: XRCC1 and HRAS, reported to have a role in thyroid cancer." (PMID 37175943, 2023). "We revealed two somatic heterozygote variations in XRCC1 and HRAS genes known to implicate thyroid cancer." (PMID 37175943, 2023). "Of note, EIF1AX mutations were found almost exclusively in HRAS-, KRAS-, and NRAS-mutant thyroid cancers (p<0.05), whereas STK11 mutations were found in greater proportion of HRAS-mutant NSCLC compared to the other HRAS-mutant cancer types." (PMID 37503077, 2023). "For instance, only two known cancer genes were found to be mutated in over 5% of thymomas (MUC16 and HRAS), testicular germ cell tumours (KRAS and KIT), and thyroid carcinomas (BRAF and NRAS)." (PMID 37550388, 2023). "As a motivating example, other studies have shown that activating mutations in Ras isoforms (HRAS, KRAS, NRAS) tend to have similar effects to one another in thyroid cancer, producing similar gene expression signatures." (PMID 35761387, 2022). "Two of the most important and common mutations found in thyroid cancer are BRAFV600E mutations and RAS-like mutations, which involve a family of three highly homologous isoforms (NRAS, KRAS and HRAS)." (PMID 35246262, 2022). "In the thyroid cancer samples BRAF mutations co-occurred less frequently than expected with mutations in NRAS, HRAS, RET, PTEN, NF1 and KRAS." (PMID 36275468, 2022). "The three isoforms of RAS (HRAS, NRAS, and KRAS) mutations are the second most common mutation encountered in thyroid carcinomas." (PMID 35197932, 2022).
thyroid cancer (continued). "The study showed that relatively few cancers harbor HRAS mutations, particularly thyroid cancer, pheochromocytoma and paraganglioma, and HNSCC, with HNSCC expressing the highest levels of HRAS transcripts." (PMID 34771475, 2021). "In adult thyroid cancer, NRAS codon 61 (NRAS Q61K) and HRAS codon 61 (HRAS Q61R) mutations are the most frequent." (PMID 33120984, 2020). "RAS (HRAS and NRAS) mutations are the second most common genetic alterations in thyroid cancers, which were mutually exclusive with BRAF mutations (the most common mutations in thyroid cancers)." (PMID 28582771, 2017). "The highly mutated genes (KRAS, HRAS, NRAS, etc.)in somatic cells of thyroid cancer were rarely observed to mutate in patients’ blood in our study." (PMID 26530882, 2015). "A meta-analysis including 2552 thyroid cancer patients from 17 studies reported an overall RAS mutation prevalence of 35.4% (95% CI: 22.7–50.7%), with NRAS being the most frequent subtype (69.5%), followed by HRAS (25.8%) and KRAS (6.9%)." (PMID 41595518, 2026). "The role of SWI/SNF disruption in thyroid cancer progression has been investigated in transgenic mice with co-mutation of SWI/SNF genes and HRAS p.G12V or BRAF p.V600E, highlighting the cooperative role of SWI/SNF in promoting loss of differentiation and tumor progression." (PMID 41175860, 2025). "Because this alternative prenylation did not affect HRAS, FTI treatment in HRAS-driven cancers has shown promise in preclinical models of thyroid cancer, rhabdomyosarcoma, and head and neck squamous cell carcinoma, and has recently entered multiple clinical trials for different HRAS-mutant cancers." (PMID 40801144, 2025). "For instance, thyroid cancers which had mutations in codons 12 or 13 of KRAS were found to be associated with comparatively lower malignant outcomes (41.7%) as compared to mutations in codon 61 of NRAS (86.8%) and codon 61 of HRAS (95.5%)." (PMID 39941320, 2025). "The MAPK1, HRAS, and PIK3CA genes are associated with distinct thyroid cancer subtypes, suggesting the intriguing hypothesis that the unobserved latent factors are germline or somatic changes in these genes themselves." (PMID 39677786, 2024). "Therefore, we conducted functional study using thyroid cancer cells with RAS mutation (KRAS mutation in Cal62 and HRAS mutation in HTH83) because high MFN2 expressed PTC are related with RAS-like gene expression." (PMID 33479369, 2021). "Tipifarnib has also recently been designated as a breakthrough therapy by the FDA for HRas mutant head and neck squamous cell carcinoma after positive results from a phase II clinical trial and has shown preclinical activity in HRas mutant thyroid cancer cell lines." (PMID 34680208, 2021). "Thus higher frequency of RAS (HRAS and NRAS) mutations was observed in thyroid cancers with high-level energy metabolism because of high-frequency A→G mutations." (PMID 28582771, 2017). "Except for BRAF, HRAS, NRAS and TG, whose involvement in PTC is deeply revealed, for the other commonly mutated genes in all tumor stages, we further assayed the relationship between TCGA data, the RNA expression level of thyroid cancer-derived cell lines and their mutational status." (PMID 35996174, 2022).